LGALS3 (galectin 3)
Diseases named in the same sentence as LGALS3 in open-access papers (continued):
Sharing a sentence is not in itself a finding about the gene and the disease.
tumor (continued). "In tumor regions where PD-1 is either blocked or PD-1 receptors are absent, Galectin-3 (encoded by LGALS3), produced by both tumor cells and macrophages, can interact with LAG3 on T cell surfaces to suppress IFN-γ secretion and induce T cell apoptosis." (PMID 40411616, 2025). "When SW620 cells, without or with galectin-3 shRNA knockdown, were applied to the chick embryo model, 70% (7/10) and 67% (6/9), respectively, embryos formed tumours when applied with SW620 and galectin-3-knockdown SW620 cells." (PMID 41023585, 2025). "Bothcompounds bind galectin-3 and -1, but only GGH suppressed tumor progressionin mice." (PMID 40841319, 2025). "In our IHC study, the one patient with confirmed pulmonary metastasis had both parafibromin- and galectin-3-negative staining on the primary tumor." (PMID 40142758, 2025). "Transcriptional programs centered on IL1B/CXCL5 and LGALS3/IDO1 define distinct immune phenotypes that may guide future combination strategies targeting both effector and suppressive arms of the tumor immune response." (PMID 40723289, 2025). "These include well-known tumor markers (e.g., CA19-9, CEA, and CA125), as well as proteins more recently described as potential novel biomarkers for the detection of PC (e.g., Beta-2 microglobulin (B2M), TIMP-1, CRP, Galectin-3, uPA, and VEGF-A)." (PMID 40563629, 2025). "Although not disease-specific, galectin-3 (Gal-3) serves as a marker of early pathological changes induced by metabolic alterations within the tumour microenvironment." (PMID 40868983, 2025). "Pectin inhibits galectin-3, a protein that plays a crucial role in cancer cell growth, adhesion, and metastasis, and inhibits matrix metalloproteinases, enzymes that disrupt the ECM and facilitate tumor cell invasion." (PMID 41249064, 2025). "In addition, proteins less abundant in the tumor, such as basigin, N-WASP, Galectin-3 (Gal-3), and chromogranin-A (CgA), were identified in this functional network." (PMID 39195201, 2024). "In addition to MHC-II, LAG-3 also binds to other ligands, such as liver sinusoidal endothelial cell lectin (LSECtin), Galectin-3 (Gal-3), and fibrinogen-like protein 1 (FGL1), which further inhibit T cell function and promote tumor immune evasion." (PMID 39743998, 2024). "The expression of Galectin-3 in non-Vδ1Vδ2 cells is also interesting, as recent studies link Galectin-3 production to a poor patient outcome in CRC, increased metastatic potential, and to a γδ17 phenotype, both in healthy tissues and tumours." (PMID 38953978, 2024). "Moreover, MUC1 can promote the phosphorylation of extracellular signal-regulated kinase 1/2 (ERK1/2) and AKT by binding to galectin-3 (GAL3), enhancing cancer cell adhesion to vascular endothelial cells and tumor invasiveness." (PMID 39491020, 2024). "Interestingly, the knockdown of galectin-3 was able to rescue hypoxia-induced upregulation of ROCK activity and subsequent tumor cell motility." (PMID 38921484, 2024). "As expected, inflammatory response, tumor inflammation signature score, and IL-10 anti-inflammatory signaling pathway were positively correlated with HCP5 and LGALS3 in HCC, implying that the high level of HCP5 or LGALS3 expression is characterized by a high immune cell infiltration." (PMID 38643145, 2024). "Previous studies revealed that in solid tumor patients, blocking LGALS3, a ligand for LAG3, in conjunction with immune approaches may promote anti-tumor immunity and boost tumor regression." (PMID 38643145, 2024). "Recently we showed that galectin-3 is a binding partner of platelet GPVI and that interaction induces platelet activation, shape change, degranulation, and ATP release, thereby inducing tumor metastasis." (PMID 36873388, 2023). "This study demonstrated that the coculture of stimulated γδ T cells with different tumor cells significantly enhanced the galectin-3 release, which did not influence γδ T-cell cytotoxicity against tumor cells." (PMID 38259448, 2023).
tumor (continued). "In the absence of zoledronate galectin-3 was slightly increased in the presence of tumor cells after 72 hours compared to 48 hours." (PMID 38259448, 2023). "Additionally, we found abundant expression of the LAG-3 ligands MHC-II and galectin-3 in diverse immune cell types, whereas FGL1 and LSECtin were minimally expressed by immune cells in the tumor microenvironment (TME)." (PMID 37795090, 2023). "In sum, comparable to Vδ2 T cells, cytotoxicity of Vδ1 T cells against tumor cells is not influenced by galectin-3." (PMID 38259448, 2023). "Galectin-3, a ligand expressed by numerous cells within the tumor microenvironment rather than the tumor itself, has the potential to interact with LAG3 on tumor-specific CD8+ T cells, thereby modulating anti-tumor immune responses." (PMID 37569880, 2023). "Galectin 3 (Gal3) binding to CHI3L1 activates the AKT/mTOR-mediated transcriptional regulatory network (NF-κB and CEBPβ), leading to an immune suppression and polarization of M2 TAMs, which then activate PD-1 and CTLA-4 to promote tumor progression." (PMID 37759870, 2023). "Instead, ICB efficacy was robustly identified through the in situ hotspot detection of galectin-3-positive non-proliferating tumor zones enriched in cell death and infiltrated by anti-tumor cytotoxic neutrophils positive for ICAM-1 and neuropilin-1." (PMID 36672243, 2023). "C1GalT1-expressing cancer cells implanted in chick embryos resulted in the formation of significantly bigger tumours than C1GalT1-suppressed cells and the presence of galectin-3 increased tumour growth of C1GalT1-expressing but not C1GalT1-suppressed cells." (PMID 37612278, 2023). "The chicken embryo is rich of capillary network and is increasingly used as an effective in vivo model in assessing tumour growth and was used here to assess the effects of C1GalT1 expression on tumour growth without and with galectin-3." (PMID 37612278, 2023). "Compared to the primary tumor, none of the analyzed features, including galectin-3, was stable and statistically significant in the metastatic lesion." (PMID 38144531, 2023). "The protein complex of Galectin-3-TF/MUC-1 induces MUC-1 cell surface polarization leading to the exposure of cell adhesion molecules, thus inducing tumor cell adhesion to the vascular endothelium which increases the number of cancer cell aggregates in the circulation." (PMID 36873388, 2023). "For example, binding of galectin-3 to the oncofoetal Thomsen-Friedenreich Galβ1,3GalNAcα-Thr/Ser (TF antigen) on the transmembrane mucin protein MUC1 enhances circulating tumour cell homotypic aggregation and survival and increases tumour cell heterotypic adhesion to vascular endothelium." (PMID 37055381, 2023). "By releasing an extracellular regulator, galectin-3, tumor cells are capable of blocking interferon gamma (IFN-γ) in the TME followed by impeding chemokines CXCL9, CXCL10, and CXCL11 leading to obstructed T-cell recruitment into the tumor bed." (PMID 35053449, 2022). "We also analyzed the transcriptomics datasets from TCGA primary tumor samples (10,496 cases in total) and GTEX normal tissue samples (7,792 cases in total) from UCSD Xena, and found that the expression level of galectin-3 was correlated with that of HK2 and PKM in all data." (PMID 36481721, 2022). "Moreover, tumor-specific adhesion molecules and antigens such as mucoprotein-1, epithelial-adhesion molecules, lymphocyte-homing receptors (like CD44), galectin-3, integrins, and cadherins are overexpressed on the surface of cancer cell membranes." (PMID 35062958, 2022). "In the present study, the mRNA expression of five galectins (LGALS1, LGALS3, LGALS4, LGALS8, and LGALS9) is explored in the tumor samples of 56 ovarian carcinoma patients, and the expression fold change was calculated in comparison to 26 adult females with normal ovaries." (PMID 36050693, 2022). "For instance, galectin-1, galectin-3, and CD47 are expressed on the tumor cell membrane." (PMID 36382024, 2022).
tumor (continued). "Overexpression of tumor galectin-3 did not have any significant effect on survival outcomes in this cohort." (PMID 35280768, 2022). "Three specific cellular ligands of NKp30 have been identified so far: BAG6, B7-H6, and galectin-3, all of which could be found on the tumor surface, but while BAG6 and B7-H6 activate NK cell cytotoxicity, galectin-3 blocks it completely." (PMID 34829829, 2021). "Upon GPVI–galectin-3 interaction, platelets express CD62P, release ATP, and migrate across the endothelium, favoring the transmigration of tumor cells, which could be reduced via GPVI blockade." (PMID 34360659, 2021). "LGALS3 and LGALS3BP are thus candidate proteins for identifying HCC tumours with increased likelihood for recurrence post-LT, which might represent potential therapeutic targets to diminish HCC recurrence post-LT." (PMID 34794390, 2021). "Galectin -3 and enolase two were significantly downregulated in the WM278 OPN-siRNAprimary tumor originated cell line (average inhibition rate 60%), in contrast, the expression of these two proteins were increased in the OPN-siRNA silenced metastasis originated WM1617 cells." (PMID 34257527, 2021). "Recently, the expression of galectin-3 was suggested as predictive of tumor aggressiveness, but its prognostic role was not yet established." (PMID 34322092, 2021). "Similar to prior results, the mean value of LAG3 (p = 0.004) and HLA-DR (p = 0.004) was higher in M3 than in D3 tumours; this was not the case for Galectin-3 (p = 0.61)." (PMID 34503258, 2021). "Secretion of galectin-3 into the ECM by tumour cells bound the inflammatory cytokine CXCL9, effectively negating the development of chemokine gradients that would otherwise guide T-cells towards the tumour cells." (PMID 33187209, 2020). "Finally, we determined that LGALS3, CD44, FN1 and EZR were upregulated in both tumour and host stromal datasets." (PMID 32493768, 2020). "Additionally, four proteins (Triosephosphate isomerase, TPI1; Galectin-3, LGALS3; Galectin-3-binding protein, LGALS3BP; Filamin-A, FLNA) showed average immunostaining in normal tissue and high in tumor tissue." (PMID 32197468, 2020). "The results indicated a positive correlation between Galectin-3 and microvascular in HCC tissues, suggesting that increased expression of Galectin-3 expression may be involved in the process of tumour angiogenesis in the HCC microenvironment." (PMID 32801345, 2020). "In contrast, all patients with negative or low/intermediate expression of galectin-3 in tumor cells showed an early and durable objective response to pembrolizumab, indicating galectin-3 as an interesting predictive marker of tumor responsiveness." (PMID 30935099, 2019). "Namely, the presence of tumor infiltrating CD3+CD8+FoxP3− T cells, galectin-9+ dendritic cells (DC)/DC-like macrophages, a high CD14+CD163− (M1)/CD14+CD163+ (M2) macrophage ratio, and the expression of galectin-3 by tumor cells." (PMID 31248118, 2019). "Based on the analysis, it was found that the Akt signaling pathway was active in tumor cells with high expression of ST6GALNAC1, and the activation of the Akt signaling pathway could be blocked by knock downing galectin-3 protein." (PMID 30996686, 2019). "Thus, next to collagen, fibronectin, fibrin, and laminin, galectin 3 seems to be an additional ligand for GPVI relevant for platelet activation and vice versa for an increase in tumor cell malignancy." (PMID 30305116, 2018). "Other parameters, such as Eastern Cooperative Oncology Group (ECOG) performance, gender, surgical method, age ≥ 50 years, tumor size ≥ 5 cm, radiation field, and expression level of galectin-3, were not significant factors." (PMID 29378529, 2018). "In the tumor microenvironment, the extracellular galectin-3 interacted with effector molecule, interferon (IFN)-γ, owing to its extensive glycosylation and dampened its protective function against the developing tumor." (PMID 30388704, 2018).
tumor (continued). "To further examine whether galectin-3 retains IFNγ within the tumor microenvironment, we performed in vivo experiments using NSG mice bearing subcutaneous human tumor xenografts." (PMID 28986561, 2017). "For instance, galectin-3 retention of glycosylated cytokines in the tumor ECM on the one hand, and T-cell dysfunction due to galectin-3 on the other hand, as suggested by a more activated T-cell phenotype observed after intratumoral injection of galectin antagonists." (PMID 28986561, 2017). "On the other hand, galectin-3 and -9 participate in the immune inhibitory checkpoints cascade, including interactions with lymphocyte activation gene (LAG)-3 or TIM-3, leading to an inhibition of tumor infiltrating T cells." (PMID 29258207, 2017). "Our study is not entirely free of galectin-3 since 4T1 tumor cells express galectin-3, which is believed to confer survival advantage to tumor cells during dissemination." (PMID 27526676, 2016). "We also examined expression levels of galectin-3 and TERT in tumor tissues from xenografted mice." (PMID 27494887, 2016). "Furthermore, the disruption of the interaction between Ras/galectin-3 reduced ERK activation, enhanced the cell cycle inhibitor p21 expression, and inhibited proliferation in vitro and tumor growth in nude mice." (PMID 27242966, 2016). "Therefore the absence of host galectin-3 may lead to a decreased immune response against the tumor and be an important predisposing factor for tumor growth in the primary site and for the dissemination of tumor cells to the lymph nodes and bone marrow compartment." (PMID 27526676, 2016). "Our results demonstrate that the absence of host galectin-3 confers a selective growth advantage to tumor cells, facilitating the metastatic spread of cancer cells to the lymph nodes and bone marrow." (PMID 27526676, 2016). "Our data demonstrated that the absence of host galectin-3 drastically affected the tumor biology favoring the metastatic spreading of 4T1 cells to inguinal lymph nodes and bone marrow colonization." (PMID 27526676, 2016). "Altogether, these data demonstrate that the absence of galectin-3 in the host confers a selective growth advantage for tumor in the primary site." (PMID 27526676, 2016). "CD8 TILs were isolated from tumour ascites and, without prior in vitro expansion, they were treated overnight with either LacNAc, a competitive binder to galectin-3, or an anti-galectin-3 antibody." (PMID 27447355, 2016). "The role of galectin-3 in the host tissue modulating the tumor biology is not completely understood." (PMID 27526676, 2016). "Relevantly supporting the galectin-3 regulation by hypoxia, almost all tumor areas away from necrotic tissues in mice were consistently negative for galectin-3 and GLUT-1 labeling in all primary lesions." (PMID 26222311, 2015). "The interaction of galectin-3 with cell surface epidermal growth factor receptor (EGFR) and transforming growth factor-β receptor (TGFβR) is also believed to contribute to the increased invasiveness of tumor cells." (PMID 25669973, 2015). "Likewise, core 2 O-glycans of MUC1 from bladder tumors are modified with poly-LacNAc, which allows them to bind to galectin-3 and hamper the access of NK cells to the TNF-related apoptosis-inducing ligand present in the tumor cells surface." (PMID 26161361, 2015). "Since galectin-1 was practically always expressed by tumor infiltrating immune cells and galectin-3 among non-tumor cells by CD163+ macrophages, the galectin-1/3 double positive cells are expected to be tumor epithelium infiltrating CD163+ macrophages." (PMID 26066796, 2015). "Once in the extracellular space, galectin-3 can interact with innumerous binding partners, mostly polylactosamine-rich molecules in the extracellular matrix (ECM) or on the cell surface, and plays key roles in the extracellular modulation of tumor progression." (PMID 24982845, 2014).
tumor (continued). "While in galectin-3-expressing microenvironments, it was possible to observe CD68-positive cells infiltrating the tumor mass, these cells were only found in the periphery of galectin-3 negative tumors engrafted in KO mice." (PMID 24421272, 2014). "As galectin-3 was shown before 9 as an important inducer of the M2 phenotype, we asked whether this lectin could modulate the phenotype of TAM within the tumor microenvironment." (PMID 24421272, 2014). "It has been reported that galectin-3 expression is induced in cirrhotic livers and HCC and that galectin-3 overexpression inhibits the immune response by inducing apoptosis in lymphocytes and thus promotes tumor growth." (PMID 25260879, 2014). "In KO animals, tumors derived from galectin-3-expressing cells were infiltrated by CD68+-cells, whereas in tumors derived from galectin-3-nonexpressing-cells, CD68+ cells failed to infiltrate tumors and accumulated in the periphery of the tumor mass." (PMID 24421272, 2014). "In fact, the absence of this lectin in both tumor cells and within the tumor microenvironment does not seem to interfere with the tumorigenic process as all galectin-3 KO mice injected with Tm1 cells developed tumors." (PMID 24421272, 2014). "The last four are important steps of the metastatic process, in which extracellular, rather than intracellular galectin-3, plays a prominent role in both tumor cells and stromal cells present in the tumor microenvironment." (PMID 24982845, 2014). "On the other hand, when galectin-3 was absent in either tumor or stromal compartment, a significant reduction in tumor growth was observed." (PMID 24421272, 2014). "We did not observe apoptosis of blood T cells, T cell clones or tumor cell lines when galectin-3 was added at 10 nM, which is the highest concentration of galectin-3 that we measured in carcinoma ascites." (PMID 24212939, 2011). "Accumulation of galectin-3 upon transformation of cells that do not express this lectin under physiological conditions has been observed in different models of tumor progression." (PMID 22216245, 2011). "In none of the studies however, were galectin-3 levels reported to stay unchanged in normal versus tumor tissue." (PMID 23658855, 2010). "Interestingly, recent studies suggest that blood-borne tumor-derived leukemia inhibitory factor (LIF) and galectin-3 (Gal3) may excite the paraventricular nucleus of the hypothalamus, leading to increased sympathetic signaling." (PMID 41030446, 2025). "Such a pattern suggests that LGALS3 may contribute to tumor maintenance and general aggressiveness, rather than specifically promoting metastasis." (PMID 41153387, 2025). "We also analyzed protein factors released in the supernatants of US-treated cancer cells, detecting well-known tumor markers (e.g., CA19-9, CEA, and CA125), as well as proteins as candidate novel biomarkers for the detection of PC, particularly B2M, CRP, TIMP1, and Galectin-3." (PMID 40563629, 2025). "The galectin-3 produced by tumor cells and macrophages blocks CD8+ T cell activation signals and induces T cell apoptosis by interacting with LAG3 on the T cell surface; while FOXP3+ Tregs suppress anti-tumor immunity by secreting various inhibitory cytokines, such as TGF-β, IL-10 and IFN-γ." (PMID 41219968, 2025). "However, in our study, we found that galectin-3 expression did not always increase in invasive tumor areas." (PMID 39451592, 2024). "This study integrated HCC scRNA-seq and RNA-seq data and developed a tumor classification signature (MPCD index) based on extensive bioinformatics analysis and machine learning algorithms, and found four prognostic genes for HCC, S100A9, FYN, LGALS3, and HMOX1." (PMID 39795978, 2024). "Galactose lectin-3 (galectin-3) and liver sinusoidal endothelial cell lectin (LSECtin), ligands for LAG3, are also important immunosuppressive checkpoints expressed on the surface of a variety of tumor cells and are involved in the regulation of CD8+ T-cell function." (PMID 37055849, 2023).